IGKV1-13 (immunoglobulin kappa variable 1-13)
Description:
V region of the variable domain of immunoglobulin light chains that participates in the antigen recognition. Immunoglobulins, also known as antibodies, are membrane-bound or secreted glycoproteins produced by B lymphocytes. In the recognition phase of humoral immunity, the membrane-bound immunoglobulins serve as receptors which, upon binding of a specific antigen, trigger the clonal expansion and differentiation of B lymphocytes into immunoglobulins-secreting plasma cells. Secreted immunoglobulins mediate the effector phase of humoral immunity, which results in the elimination of bound antigens. The antigen binding site is formed by the variable domain of one heavy chain, together with that of its associated light chain. Thus, each immunoglobulin has two antigen binding sites with remarkable affinity for a particular antigen. The variable domains are assembled by a process called V-(D)-J rearrangement and can then be subjected to somatic hypermutations which, after exposure to antigen and selection, allow affinity maturation for a particular antigen.
Synonyms: IGKV113; L18
Gene: Immunoglobulin variable (V) pseudogene on chromosome 2 (89,045,995 to 89,046,466, reverse strand). Ensembl gene ENSG00000253497.
Subcellular location: Secreted; Cell membrane
Diseases named in the same sentence as IGKV1-13 in open-access papers:
IGKV1-13 is named in the same sentence as 1 disease in open-access papers, as found by Europe PMC text mining. Sharing a sentence is not in itself a finding about the gene and the disease.
IGKV1-13 shares sentences with these, for which no sentence is quoted: Hepatic steatosis (1 paper).